INS (insulin)
Diseases named in the same sentence as INS in open-access papers (continued):
Sharing a sentence is not in itself a finding about the gene and the disease.
Insulin resistance (continued). "Furthermore, our ex vivo GSIS results demonstrated that islets from aged mice exhibited reduced insulin secretion even at the basal glucose concentration compared with young mice, which is in line with age-associated insulin resistance." (PMID 38794702, 2024). "Insulin resistance can cause hyperglycemia and an increase in insulin levels throughout the body." (PMID 38643133, 2024). "In turn, increased lipid accumulation in the liver and skeletal muscles may impair insulin signaling and cause insulin resistance." (PMID 39057041, 2024). "Additionally, we found that HGU and EGP were associated with body adiposity and whole-body insulin resistance markers (fasting insulin, HOMA-IR, and M-value)." (PMID 38989003, 2024). "Additionally, exogenous insulin administration often causes “iatrogenic hyperinsulinemia,” leading to whole-body insulin resistance and increased risk of cardiovascular complications." (PMID 38989268, 2024). "Furthermore, the HFD caused increases in TG, TC, LDL + VLDL, insulin, insulin resistance, cardiovascular risk indicators including AC, AI, CAI, and CRR, and glucose." (PMID 39519447, 2024). "This stress could stem from TB’s known association with insulin resistance or a compromised insulin secretion, which not only affect glucose utilisation and energy production but also impact the body’s overall metabolic balance." (PMID 39014031, 2024). "Importantly, in obesity, higher numbers of adipose tissue eosinophils are associated with decreased insulin resistance, possibly by increasing insulin sensitivity." (PMID 39316677, 2024). "Additionally, E3 ubiquitin ligases indirectly influence insulin signaling by targeting pro-inflammatory mediators linked to insulin resistance." (PMID 39188976, 2024). "Non-insulin-based insulin resistance indices are significantly associated with the risk of DN." (PMID 39720248, 2024). "Abnormal maternal immune adaptation is key to the low-grade inflammation associated with the diagnosis of GDM, while immune cell infiltration of visceral adipose tissue causes the pathological dysregulation of insulin signaling and contributes to insulin resistance." (PMID 38706698, 2024). "These improvements in hepatic insulin sensitivity could be caused by a reduction in hepatic steatosis a well-known factor to be associated with hepatic insulin resistance." (PMID 38796310, 2024). "According to the researchers, one cluster (highest insulin resistance) showed more association to kidney disease, another cluster (insulin deficient) showed the highest risk of retinopathy, while a third cluster associated with higher fat liver, indicating a relevance of VAT to IR." (PMID 38590830, 2024). "It is possible that antipsychotic effects that are associated with insulin resistance could reach beyond the insulin signaling pathway due to the unique aspects of these drugs." (PMID 38791018, 2024). "Moreover, aging and systemic insulin resistance are associated with a decline in the cerebrospinal fluid (CSF) to plasma insulin ratio and a reduction in insulin receptor expression." (PMID 39596023, 2024). "that included lean and overweight sedentary individuals, researchers reported that Blautia and Dorea were significantly associated with insulin sensitivity indices (plasma insulin and homeostatic model assessment of insulin resistance (HOMA‐IR)) in their overweight subjects only." (PMID 38514894, 2024). "Thus, exercise and weight loss result in greater improvements in insulin sensitivity, particularly for those with some levels of insulin resistance." (PMID 38473112, 2024). "Insulin resistance is the most important factor in the pathophysiology of this type; however, a relative deficiency of insulin may have contributed to its development." (PMID 39328924, 2024).
Insulin resistance (continued). "The observed reduction in body weight in the intervention group in our study was notably associated with improved insulin metrics, including decreased fasting insulin and insulin resistance, as well as increased insulin sensitivity, when OJ enriched with vitamin D3 and probiotics was consumed." (PMID 38732578, 2024). "The underlying mechanism relates to insulin resistance and hyperinsulinemia, which may stimulate the carcinogenic pathways of insulin." (PMID 38804394, 2024). "In addition, normal insulin-mediated lipoprotein lipase activation is diminished in insulin resistance where patients are relatively insulin deficient and particularly in those with poor glycemic control." (PMID 38846018, 2024). "Although the association between adipose eosinophils and reduced insulin resistance has been demonstrated in previous studies, our findings highlight the downstream effects, particularly the reduction of circulating insulin and its impact on airway function." (PMID 39316677, 2024). "In addition, lower serum amylase has been associated with decreased insulin and the development of insulin resistance in middle‐aged humans." (PMID 38955666, 2024). "This may be due to the hormonal imbalances associated with PCOS, including hyperinsulinemia (elevated insulin levels) and insulin resistance." (PMID 39355538, 2024). "This can diminish insulin sensitivity and elevate insulin resistance risk." (PMID 38761298, 2024). "Additionally, many molecular studies have demonstrated that insulin-stimulated muscle glucose uptake is highly susceptible to insulin resistance due to impaired GLUT4 translocation." (PMID 39624846, 2024). "Considering the long-term damage on cardiac function caused by insulin resistance and insufficient insulin signaling, it is essential for future research to explore the utility of dynamic monitoring of the TyG index or cumulative TyG index in patients who have undergone PCI." (PMID 38952542, 2024). "T2D is mainly caused by insulin resistance as well as impaired insulin production and secretion." (PMID 39695759, 2024). "Insulin mediates peripheral vascular functions (e.g., vasodilation) via its receptors and signalling pathways, and is associated with vascular complications in insulin resistance (see29 for review of mechanism)." (PMID 38914735, 2024). "Chronic exposure of bitches to estradiol and P4 caused insulin resistance in the whole body, but primarily in the skeletal muscle, and the estrogenic phase of the canine estrus cycle was associated with reduced peripheral (mainly muscle) insulin sensitivity." (PMID 38539988, 2024). "Reduced insulin sensitivity constitutes a potential constituent, as evidence suggests that oxidative stress and inflammation instigated by obesity are intricately associated with the emergence of both localized and systemic insulin resistance." (PMID 39764243, 2024). "Although the etiology and pathogenesis of T2DM remain unclear, its occurrence is related to insufficient insulin secretion or insulin resistance (IR), which is often closely associated with glucose and lipid metabolism." (PMID 39062577, 2024). "Regarding type 2 DM (T2DM), insulin resistance (IR) and hyperinsulinemia have mainly been implicated in the pathogenesis of reproductive dysfunctions, as insulin can act as gonadotropin on the theca cells of the ovary and can lead to hyperandrogenism and inhibition of proper ovulation." (PMID 38353886, 2024). "Insulin resistance (IR) refers to a state of hyperinsulinemia caused by a variety of reasons, in which the compensatory secretion of insulin is increased to maintain a stable level of blood glucose in the body due to a decrease in the ability of insulin to take in and utilize glucose." (PMID 38348417, 2024).
Insulin resistance (continued). "Type 2 diabetes (T2D) is a disease characterized by heterogeneously progressive loss of islet β cell insulin secretion usually occurring after the presence of insulin resistance (IR) and it is one component of metabolic syndrome (MS), and we named it metabolic dysfunction syndrome (MDS)." (PMID 39353925, 2024). "Increased IMCL is linked with insulin resistance pathology and therefore, it is possible that oxidation of these lipids may explain the greater insulin sensitivity improvements experienced by men at the same weight-loss point." (PMID 39275236, 2024). "In another study, the DII was found to be positively associated with fasting plasma glucose, fasting serum insulin, and the homeostatic model assessment of insulin resistance, and a more pro-inflammatory diet was associated with increased odds of insulin resistance and prediabetes." (PMID 39206319, 2024). "Propofol, a common anesthetic used in the ICU, may cause hyperglycemia by inducing insulin resistance, reducing insulin-stimulated glucose uptake in muscles, and attenuating insulin-mediated suppression of hepatic glucose." (PMID 39712697, 2024). "Its secretion is strongly related to insulin resistance linked to obesity, as its levels increase in genetic or diet-induced obesity due to its effects on glucose metabolism, which are antagonistic to those of insulin, increasing hepatic glycogenesis." (PMID 38612504, 2024). "Insulin resistance may be caused by a reduction of insulin receptors or receptor dysfunction, leading to decreased efficiency of insulin signal transduction." (PMID 39107318, 2024). "Excess saturated fat may increase the risk of central obesity, cause ectopic deposition of serum-free fatty acids, inhibit insulin signaling, lead to insulin resistance, and elevate blood glucose levels." (PMID 39267858, 2024). "Moreover, findings from a Drosophila model have reported that IGFBP and its homolog, ImpL2, interrupt systemic insulin signaling, which induces insulin resistance and skeletal muscle loss." (PMID 38791998, 2024). "T2DM and frailty share pathophysiological mechanisms, such as chronic hyperglycemia and changes in insulin levels that lead to alterations in the metabolism of carbohydrates, fats, and proteins, which in turn lead to insulin resistance and a deficit of insulin secretion with protein loss in muscles." (PMID 39330347, 2024). "A cross-sectional study aimed at examining the association between obesity, insulin sensitivity, metabolic syndrome, and lung function among American adolescents found that insulin resistance was negatively correlated with FEV1 and FVC in subjects with and without asthma." (PMID 38398863, 2024). "Insulin resistance may be due to different factors, such as mutations in insulin signaling pathways, autoimmune reactions and environmental factors." (PMID 38397072, 2024). "This is also confirmed by the association of insulin sensitivity/reduction of insulin resistance as a favorable outcome for interventions targeting the Hallmarks of Aging “Disabled macroautophagy”, “Deregulated nutrient-sensing”, and “Mitochondrial dysfunction”." (PMID 38630692, 2024). "Insulin resistance of alpha cells may decrease the inhibitory effects of insulin on glucagon secretion; additionally, loss of beta-cell mass could decrease local levels of insulin in the fed state." (PMID 38579751, 2024). "Previous studies on the relationship between dietary fibre intake and androgen levels and metabolic indices in adult women with PCOS showed that fibre intake was inversely associated with insulin resistance, fasting insulin, glucose, testosterone, and DHEA-S60." (PMID 38347150, 2024). "Nevertheless, in pregnant women with a higher BMI, the pre-existing insulin resistance may exacerbate, causing the pancreatic beta cells to be unable to adequately respond by producing more insulin." (PMID 39035594, 2024).
Insulin resistance (continued). "The short-term effects of rapid weight loss, such as a reduced metabolic rate and alterations to insulin and leptin levels, may prelude the more pronounced metabolic disturbances that occur during weight regain, such as insulin resistance." (PMID 38392975, 2024). "In addition, obesity caused higher levels of fasting insulin, which was also reflected in a higher homeostatic model assessment of insulin resistance (HOMA-IR) score and lower McAuley index." (PMID 38256185, 2024). "Insulin resistance has been linked to the etiology of depression, and metformin’s potential to improve insulin sensitivity might contribute to its antidepressant effects." (PMID 39682734, 2024). "Insulin resistance, and high levels of insulin and glucose are associated with mitochondrial dysfunction, neuroinflammation, neurotransmitter imbalances, glucose hypometabolism, and lower volume in parts of the brain, all of which are also associated with mental disorders." (PMID 39539363, 2024). "Moreover, T2DM is often associated with insulin resistance, making direct insulin injections less effective." (PMID 39125375, 2024). "The scientific literature consulted and used to write the article was found in PubMed, Scopus, Science Direct, etc. using the following keywords: insulin, insulin signaling, insulin resistance, hyperinsulinemia, cardiovascular risk factors, cardiovascular diseases, cardiovascular system." (PMID 38545338, 2024). "This pathology is associated with several clinical complications and is characterized by an insulin deficit caused by the pancreatic dysfunction of β-type cells, the development of insulin resistance in target organs, decreased protein levels of insulin receptors, and a chronic inflammatory state." (PMID 39062550, 2024). "TNF-α, a crucial contributor to insulin resistance, suppresses the activity of insulin receptor tyrosine kinase and causes the phosphorylation of insulin receptor substrate 1, weakening insulin signaling, which in turn triggers metabolic disorders associated with obesity." (PMID 39116149, 2024). "Insulin resistance is a characteristic that causes the body to react to insulin less effectively." (PMID 38255264, 2024). "Chromium is also present in the diet and may increase insulin secretion, causing hyperinsulinemia, insulin resistance, and weight gain." (PMID 39125340, 2024). "T2DM is mainly characterized by high levels of glucose in the blood (termed hyperglycemia), deficiency of insulin secretion, or insulin resistance and may be caused by a combination of genetic or environmental factors." (PMID 37880477, 2024). "Poor diet will cause an increase in blood glucose, a small fluctuation in blood glucose can trigger a huge change in insulin-producing cells thus causing an elevation in insulin levels, causing hyperinsulinemia to be the primary symptom of insulin resistance in its early phases." (PMID 39179999, 2024). "Besides BCAA and glutamate dipeptides there were a few other amino acids that have previously been associated with the insulin resistance phenotype that were decreased in the with improved insulin status including lysine and tyrosine." (PMID 39687851, 2024). "We suggest that this may be related to the fact that high dietary selenium intake increases MAFLD risk by modulating dysregulation of insulin biosynthesis and secretion as well as stimulating glucagon secretion, insulin resistance and dyslipidemia." (PMID 38435294, 2024). "The increased postprandial levels of insulin and glucose may be associated with higher risk of insulin resistance and type 2 diabetes mellitus." (PMID 38392349, 2024). "Among normal-weight and participants with overweight/obesity, increased total fat mass and trunk fat mass during growth from age 15 to 24 years were associated with increased fasting insulin concentration and insulin resistance but with decreased fasting glucose." (PMID 38173399, 2024).
Insulin resistance (continued). "A growing number of studies indicate that the metabolic disorders, especially those associated with the inappropriate secretion of insulin, and insulin resistance and obesity cause significant disturbances in the secretion and action of angiotensin peptides and vasopressin." (PMID 38279313, 2024). "Moreover, adipocytokines play a central role in regulating insulin resistance, inflammation, and immunity leading to the conclusion that insulin secretion is associated with external load at a chronic response level." (PMID 38466679, 2024). "As insulin resistance and hyperinsulinemia appear to be important risk factors for AS, measures improving insulin sensitivity, such as weight control and exercise, might be effective in the prevention of aortic stenosis." (PMID 39593205, 2024). "In conclusion, higher serum myostatin levels are independently associated with lower insulin sensitivity in adults with overweight/obesity and may be a marker of or play a mechanistic role in the development of insulin resistance." (PMID 39261976, 2024). "Moreover, IMD deficiency increased FBG, fasting serum insulin levels, insulin resistance, serum levels of triglycerides, and total cholesterol in HFD-fed, IMD−/− mice versus HFD-fed WT mice." (PMID 39338366, 2024). "Human cohort studies consistently show that offspring exposed to intrauterine hyperglycemia (from GDM, T2D, or type 1 diabetes) are at increased risk of obesity, insulin resistance, impaired insulin secretion, T2D, and cardiovascular dysfunction compared to children from the background population." (PMID 39389786, 2024). "Type II diabetes mellitus (T2DM), which accounts for about 90% of cases, is associated with the progressive impairment of insulin secretion by pancreatic β-cells and the development of peripheral tissue resistance to insulin (insulin resistance) and consequently elevated blood glucose levels." (PMID 39407644, 2024). "The resultant need for exogenous insulin therapy to control clinical signs and to avoid diabetic complications and death after the resolution of insulin-resistance causes is often attributable to glucotoxicity, a phenomenon associated with beta-cell death after chronic exposure to hyperglycemia." (PMID 38539988, 2024). "Insulin resistance in the brains of PD patients, resulting in defective insulin signaling pathways, may be linked to PD pathogenesis." (PMID 38256693, 2024). "Insulin signaling may represent the intersection of irisin’s pleiotropic effects on health, as demonstrated in cases of muscle mass loss and age-related insulin resistance." (PMID 39769243, 2024). "Fewer than 1% of patients with type 1 diabetes achieve normal glycemic control (HbA1c < 5.7%/<39 mmol/mol) and exogenous insulin administration often causes “iatrogenic hyperinsulinemia,” leading to whole-body insulin resistance and increased risk of cardiovascular complications." (PMID 38989268, 2024). "Several studies indicate that resistance exercise may be especially beneficial for people with T2DM because they increase insulin activity, while reducing the risk of low-grade inflammatory disorders like atherosclerosis, obesity, and insulin resistance." (PMID 39295999, 2024). "Insulin resistance is manifested by reduced sensitivity of muscle, liver, and adipose tissue to insulin stimulation, causing glucose metabolism disorder and leading to compensatory insulin elevation and hyperinsulinemia." (PMID 39076779, 2024). "On the other hand, SWS loss can decrease insulin secretion and increase insulin resistance." (PMID 39597994, 2024). "Furthermore, GK is implicated in insulin metabolism, which in its absence or mutation correlates with increased insulin resistance." (PMID 39199385, 2024).